RNU4-12P (RNA, U4 small nuclear 12, pseudogene)
Gene: Small nuclear RNA gene on chromosome 6 (85,993,021 to 85,993,159, reverse strand). Ensembl gene ENSG00000202103.
Homologues: Orthologues: chimpanzee U4 (99% identical), tropical clawed frog U4 (86% identical), tropical clawed frog U4 (85% identical), tropical clawed frog U4 (84% identical), tropical clawed frog U4 (83% identical), guinea pig U4 (82% identical), tropical clawed frog U4 (82% identical), tropical clawed frog U4 (81% identical), macaque U4 (77% identical), tropical clawed frog U4 (76% identical). Paralogues in human: RNU4-84P (90% identical), RNU4-70P (86% identical), RNU4-68P (84% identical), RNU4-42P (82% identical), RNU4-58P (81% identical), RNU4-76P (80% identical), RNU4-13P (79% identical), RNU4-67P (78% identical), RNU4-7P (78% identical), RNU4-35P (78% identical), RNU4-45P (78% identical), RNU4-8P (78% identical), and 81 more.